IGF2 (insulin like growth factor 2)
Diseases named in the same sentence as IGF2 in open-access papers (continued):
Sharing a sentence is not in itself a finding about the gene and the disease.
diabetes (87 papers, 2007 to 2025). "Common causes of hypoglycemia in adults are Type 1 diabetes mellitus; certain drugs; sepsis; liver, heart, or kidney failure; cortisol deficiency; and mesenchymal tumors expressing insuline like growth factor 2 (IGF2)." (PMID 38534968, 2024). "The gene enrichment pathway analysis (GEPA) revealed the involvement of insulin-like growth factor 2 mRNA binding proteins and diabetes pathways associated with the lncRNA H19." (PMID 38616192, 2024). "IGF2, a growth factor capable of binding the insulin receptor and implicated in diabetes, was among the highest transcripts expressed in responding patient tumors (eFigure 6D in Supplement 2)." (PMID 38095878, 2024). "The USP53 genes has a greater involvement in cholestatic liver disease and the IGF2 proteins are widely known as the diabetes associated protein and can control the insulin secretion in β-cells during fasting." (PMID 35277538, 2022). "IGF2BP1 can interact and process the IGF2 transcripts, and its dysfunction was associated with tumorigenesis, drug resistance, and diabetes as well as insulin control." (PMID 34203267, 2021). "One area that remains poorly understood is if, and how, fetal growth control genes expressed in the β-cell, such as Igf2, are involved in programming of diabetes susceptibility in later life." (PMID 33833312, 2021). "Elevated IGF2 predisposes patients to diabetes and is believed to be involved in the association between diabetes and increased breast cancer incidence in African-American women." (PMID 29736175, 2018). "Insulin reduced MTMR7 protein levels in human CRC cell lines, and CRC patients with type 2 diabetes mellitus (T2DM) or loss of imprinting (LOI) of insulin-like growth factor 2 (IGF2) had an increased risk for MTMR7 loss." (PMID 27409167, 2016). "We have previously demonstrated in mice that the hyperglycemic intrauterine environment of GDM can increase the risk of diabetes in offspring by altering Igf2/H19 imprinting in islets." (PMID 27888796, 2016). "Increased IGF2 expression in the fetal liver has been associated with fetal undernutrition and neonatal diabetes, and possible HF feeding during pregnancy." (PMID 25135621, 2014). "Previous studies in other countries have shown that polymorphisms from the insulin – IGF2 region can predispose to some complex pathological traits, particularly those involving diabetes." (PMID 21637566, 2010). "sVariations in the function of IGF2 may have an impact on the utilization and regulation of glucose, which may have implications for the risk of developing diabetes." (PMID 38737102, 2024). "Diabetes also caused reduced levels of IGF-2 and IGF-1 in the vitreous fluid." (PMID 38300646, 2024). "IGF-2 has high structural homology with insulin and is produced in the liver and other tissues; symptoms similar to Type 2 diabetes (including hyperinsulinemia and mild hyperglycemia) are observed in transgenic mice that overexpress IGF-2 in β-cells causing β-cell dysfunction that leads to diabetes." (PMID 35804599, 2022). "Given diabetes is one of the strongest risk factors for the development of AD and a common comorbidity, dysregulation of IGF2 signaling through IGF2R may contribute to the neuropathology of AD." (PMID 33704916, 2021). "Among those were IGF1 and IGF2, which already have stronger associations to diabetes." (PMID 32735660, 2020). "Therefore, the aim of the present study was to investigate the association between intra-prostatic levels of IGF-1, IGF-2 as well as to evaluate the role of locally expressed IGFBP-3 in BPH development in pre-diabetes." (PMID 24367483, 2013). "An increase in IR‐A could thus enhance IGF2‐mediated mitogenic signalling and decrease metabolic insulin signalling, which has been suggested as a cause of insulin resistance during the progression of diabetes." (PMID 33742502, 2021). "Thus, loss of IGF-2/IR-dependent neurotrophic support could be a common feature of sensory neuropathies in diabetes." (PMID 33915127, 2021).
diabetes (continued). "IGF2 was overexpressed in the islets of F1 and F2 generations and was hypermethylated in different CpG sites, which may cause mitochondrial dysfunction, reduction of β-cell mass and susceptibility to diabetes over multiple generations." (PMID 34828259, 2021). "Igf2 is an imprinted gene in humans that plays a key role in the development of diabetes and the inhibition of Igf2, and it has been found to be involved in maternal hyperglycemia." (PMID 39997932, 2025). "IGF2 dysregulation in diabetes similarly alters glucose metabolism and enhances glucose influx, reflecting a shared feature between diabetes and CRC." (PMID 40141058, 2025). "And, the gene IGF2 BP2, which plays an important role with metabolism associated to the susceptibility of diabetes, found only in the Tamaulipas population." (PMID 40997121, 2025). "We conducted a comparative analysis of baseline marker levels between the study and control groups, including adiponectin, leptin, IL6, TNFα, IGF1, and IGF2, while also adjusting for BMI, parity, and diabetes." (PMID 38339282, 2024). "In the context of diabetes, IGF-2 mRNA levels in the retina decreased, while IGF-1 or IR mRNA levels remained unaffected." (PMID 38300646, 2024). "Increased levels of IGF2 in comparison to controls, in multiple diseases including cancer and diabetes have been detected." (PMID 36982475, 2023). "Other established regulators of beta cell function and genes involved in monogenic diabetes or T2D risk were identified among the screening hits, such as NKX2.2, SLC2A2, PPP1R15B and IGF2 28–35." (PMID 36543916, 2023). "Serum IGF-2 content was examined by immunoblotting from sera of control and diabetic animals after 4 weeks of diabetes." (PMID 33915127, 2021). "In vivo, Igf2 transcription is also detected in the thymus of diabetes-resistant BB rats characteristically resistant in the spontaneous development of autoimmune diabetes." (PMID 33415360, 2021). "IGF2/IGF2R signaling has been implicated in metabolic regulation and diabetes risk with circulating IGF2R associated with type two diabetes mellitus (T2DM)." (PMID 33704916, 2021). "Initial studies revealed persistent Igf1, Igf2, Ins, and IR transcript levels in the retina and liver during postnatal development and experimental diabetes." (PMID 33915127, 2021). "Abnormal regulation of IGF2 leads to various types of cancers and metabolic disorders like BC, pancreatic cancer, diabetes and endocrine related disorders." (PMID 33216823, 2020). "Abnormal methylation of IGF2 leads to various metabolic disorders like BC, pancreatic cancer, diabetes and endocrine related disorders." (PMID 33216823, 2020). "For example: IGF1, IGF2 and LEPR, which have previously been associated with diabetes, while STAT5B and ROCK1 have shown weaker associations to the disease." (PMID 32735660, 2020). "IGF2BP2 can be activated by mTOR and promotes its binding to IGF2 mRNA of IGF2 thereby leading to diabetes mellitus." (PMID 29736175, 2018). "To identify factors which influence MTMR7 expression, we analysed a second independent cohort of CRC patients with metabolic parameters known to activate RTK signaling: type 2 diabetes mellitus (T2DM) and loss of imprinting (LOI) of the IGF2 gene in the tumor." (PMID 27409167, 2016). "The differences in maternal disorder (GDM versus diabetes) and birth weight are the possible factors for the different methylation in IGF2 in human and mice." (PMID 26840070, 2016). "Igf2 transcription is defective in the thymus of diabetes-prone bio-breeding rats, and tolerance to insulin is severely decreased in Igf2−/− mice." (PMID 26175734, 2015). "As already cited, a defect of Igf2 expression in the thymus was suggested to play a role in the development of autoimmune diabetes in the diabetes-prone BB rat." (PMID 26175734, 2015). "Contrary to Igf1 and Ins2, Igf2 transcription is defective in the thymus of diabetes-prone of bio-breeding (BB) rats, one of the two animal models of T1D with the NOD mouse." (PMID 26175734, 2015).
diabetes (continued). "Structural studies elucidate how each of the three ligands, insulin, IGF-1, and IGF-2, interacts differently with isoforms A and B of the insulin receptor and with type I IGF receptor and explain how these protagonists contribute to diabetes-associated cancer." (PMID 23983688, 2013). "The aim of the present study was to investigate the association between intra-prostatic levels of IGF-1, IGF-2 and BPH, as well as to evaluate the role of locally expressed IGFBP-3 in BPH development in different states of pre-diabetes." (PMID 24367483, 2013). "The insulin-like effect of IGF-2 hypersecretion from the enlarging tumor could have possibly contributed to his initial rapid glycemic improvement and apparent remission of diabetes." (PMID 41179270, 2025). "Unsurprisingly, IGF-2 has been demonstrated to ameliorate disease in various models of diabetes." (PMID 39022651, 2024). "Furthermore, insulin-like growth factor 2 (IGF2) has been found to be decreased in the serum of individuals with diabetes." (PMID 38813031, 2023). "Taken together, these data led us to hypothesize that IGF-1 and/or IGF-2 may be important endogenous ligands of the retinal IR and play a critical prosurvival role in retinal neurons, a function disrupted by diabetes." (PMID 33915127, 2021). "Insulin resistance and alterations in IGF-1 and IGF-2 have been implicated in MDD and may explain the three- to four-fold increase in depression in patients with diabetes." (PMID 34335334, 2021). "Moreover, we observed that diabetes reduces both retinal Igf2 mRNA content and IGF-2 protein content in the vitreous." (PMID 33915127, 2021). "In addition, rats with 4 weeks of diabetes and age-matched controls have equivalent serum IGF-2 content, whereas mature IGF-1 is dramatically reduced in the same animals." (PMID 33915127, 2021). "Collectively, these data reveal that IGF-2 is the primary ligand that defines basal retinal IR activity and suggest that reduced ocular IGF-2 may contribute to reduced IR activity in response to diabetes." (PMID 33915127, 2021). "Taken together with the association of IGF2R gene polymorphism and soluble IGF2R to diabetes in the present study, further investigation to elucidate how soluble IGF2R fits in the complex system of IGF and how IGF2 together with IGF2R influence the susceptibility to type 2 DM is warranted." (PMID 25922844, 2015). "Therefore, we injected recombinant mature and pro-IGF-2 intravitreally in rats with diabetes." (PMID 33915127, 2021). "A genetic defect in intrathymic expression of Igf2 is associated with autoimmune diabetes in BBDP (BioBreeding Diabetes Prone) rats, which may contribute to the absence of central T cell self-tolerance to the insulin hormone family." (PMID 34361972, 2021). "Thus, deregulation of the IGF2 and adhesion-mediated signaling may explain dysfunctions observed in diabetes." (PMID 32934005, 2020). "In addition, murine diabetes influenced placental expression of Igf2." (PMID 25269528, 2014). "We collected the liver from 8-week-old male mice and found that the relative mRNA levels of IGF2 and H19 were both significantly lower in GDM-F1 male mice, which was consistent with the islet results previously published in Diabetes." (PMID 35432202, 2022). "The results of Western blot validation showed that dynamic changes in proteins, such as IGF2, Ly6a, Grb10, and UBD, occurred to regulate the incidence of diabetes by influencing the insulin receptor substrate (IRS) signaling pathway." (PMID 30131712, 2018). "We then evaluated the effects of IGF1 (Insulin-like growth factor 1), IGF2 (Insulin-like growth factor 2), EGF (Epidermal Growth Factor) and glargine (an insulin analogue used in the treatment of diabetes) on PIP3 production in the MCF-7/B2 clone." (PMID 24647478, 2014). "Transcription of insulin-related genes (Ins, Igf1, and Igf2) has been analyzed in the thymus of diabetes-resistant (BBDR) and diabetes-prone (BBDP) rats, another model of T1D." (PMID 21647405, 2011).
diabetes (continued). "Nevertheless, diabetes reduced total rat vitreous IGF-2 content by 78%, and mature IGF-2 by 80%." (PMID 33915127, 2021). "Thus, the reduction of serum and vitreous IGF-2 and IGF-1 by diabetes is specific relative to the overall increase in vitreous protein and not likely because of IGF binding proteins." (PMID 33915127, 2021). "Diabetes reduced retinal IGF-2, but not IGF-1 or IR, mRNA levels, and reduced IGF-2 and IGF-1 content in vitreous fluid." (PMID 33915127, 2021). "Insulin-like growth factor 2 (IGF2) can activate tyrosine kinase upregulation by binding to IGF1, and it also leads to a decrease in the activity of insulin receptor substrate (IRS1), which can result in the development of diabetes." (PMID 30131712, 2018). "Longitudinal measurements of renal and systemic concentrations of IGF2 and IGFBP2 in diabetes and diabetic nephropathy will be needed to clarify which of these potential mechanisms results in the independent relation between higher circulating IGFBP2 and more adverse renal outcome over time." (PMID 23781310, 2012). "A study in STZ-induced diabetes rats reported an increase in serum and kidney IGF2 concentrations after the onset of diabetes, but without an increase in renal IGF2 mRNA expression." (PMID 23781310, 2012). "When using lower AFB1 concentrations and different cell lines, IGFR1 and IGF-2 were up-regulated; however, a recent study that correlated the exposure to AFM1 and the presence of metabolic disorders in a human population, including diabetes mellitus, corroborates our findings." (PMID 35878173, 2022). "Diabetes did not alter the content or pattern of IGF-2 in the retina." (PMID 33915127, 2021). "In conclusion, the lack of IGF-1 and the elevated levels of IGF-2 within the basal layer of the epidermis of diabetic patients may be important in delayed wound healing in diabetes mellitus, particularly for chronic foot ulcers." (PMID 23671876, 2013). "Further research is needed to understand the influence of diabetes on native PDL-MSCs on the molecular level and whether using growth factors such as IGFs or their binding proteins would enhance periodontal regeneration in diabetics, in particular IGF-1, IGF-2 and IGFBP-5." (PMID 34940355, 2021). "However, Igf2 transcripts and IGF2 protein are absent in the thymic microenvironment of a large majority (around 85%) of diabetes-prone BB rats in close correspondence with the rate of diabetes incidence in this BB strain." (PMID 33415360, 2021). "Diabetes also reduced the vitreous IGF-binding protein 3 content by approximately 60%, so changes in binding proteins likely do not account for the reduction of IGF-2." (PMID 33915127, 2021). "It is not clear whether plasma levels of IGF-2 change in diabetes, but like IGF-1, the level of IGF-2 in wound fluid is decreased." (PMID 23671876, 2013).
hepatocellular carcinoma (74 papers, 2003 to 2026). A malignant tumor that arises from hepatocytes. "In humans, IGF2 is located in the 11p15.5 imprinted locus, which is the second most frequently altered locus in hepatoblastomas and hepatocellular carcinomas, mostly through copy-neutral loss of heterozygosity." (PMID 37414763, 2023). "This is confirmed in vitro, where IGF2 treatment of HepG2 hepatoma cells decreases DNA repair enzyme expression and causes DNA damage." (PMID 35615981, 2022). "Specific hypomethylation of the IGF-2 gene in hepatocytes and peripheral blood mononuclear cells is a risk predictor of hepatic carcinoma in patients with hepatitis C cirrhosis." (PMID 36358907, 2022). "IGF2 mRNA binding protein 2 (IGF2BP2/IMP2) was originally identified as an autoantigen in hepatocellular carcinoma but has also recently been implicated in esophageal adenocarcinoma." (PMID 34503162, 2021). "However, in hepatocellular carcinoma cells the scenario observed seems to be the contrary, since the epithelial phenotype was strongly associated with expression of IGF-2 and IR as well as activation of IGF-1R and IR." (PMID 24282611, 2013). "Upregulation of H19 and Igf2 expression has been shown in HBV-associated HCC and an imbalance in H19 and Igf2 expression associated with hepatocellular carcinoma progression." (PMID 25861629, 2015). "The mechanism was thought to be the interaction of pasireotide with a high proportion of somatostatin receptor type 5 (SSTR5) expressed in hepatocellular carcinoma, leading to the lowering of IGF-2 levels." (PMID 41209155, 2025). "More recently, it was shown that 2,3,7,8-Tetrachlorodibenzo-p-dioxin (TCDD) was able to trigger the onset of hepatoma in a rodent model via specific induction of IGF2 transcription, concomitant with the increase in C/EBPβ promoter activity." (PMID 37371750, 2023). "IGF-2 has been observed to be activated and expressed inappropriately in several malignancies, including but not limited to hepatocellular carcinoma, colon cancer, liposarcoma, and embryonic tumors." (PMID 37393293, 2023). "As previously discussed in relation to the role of H3K27 methylation, the Menin/MLL complex has been shown to play a role in the activation of IGF2 p3 and p4 promoters in hepatocellular carcinoma." (PMID 37371750, 2023). "In diethylnitrosamine (DENA)-induced hepatocellular carcinoma rat models, IGF-2 levels were higher in rat liver tumors than in normal rat liver." (PMID 33669204, 2021). "In conclusion, miR-100 and miR-125b have tumor suppressor role in hepatocellular carcinoma through inhibiting IGF2 expression and activation of the AKT/mTOR pathway." (PMID 33293585, 2020). "In hepatocellular carcinoma, miR-615-5p was able to target IGF2 and SHMT2 and inhibited cell proliferation, invasion, and metastasis." (PMID 30287504, 2018). "The IGF2 mRNA binding protein IMP2/IGF2BP2/p62 was originally identified as an autoantigen in hepatocellular carcinoma." (PMID 27391348, 2016). "MiR-615-5p is located within CpG islands of the HOXC5 gene intron at chromosome 12q13.13 and functions as an outstanding tumor suppressor in hepatocellular carcinoma via inhibition of insulin-like growth factor 2 (IGF-2)." (PMID 27240340, 2016). "It is known that epigenetic alterations of IGF2 is correlated with severity of hepatocellular carcinoma development and progression." (PMID 25077705, 2014). "In hepatocellular carcinoma, the IGF-2/IGF-1R signal was shown to be involved in Nanog-mediated self-renewal of hepatic CSCs." (PMID 23663564, 2013). "Real-time PCR analysis revealed that the mRNA level of IGF2 was markedly increased (> 3-fold induction compared to normal livers) in 23/36 (64%) of HB and 3/9 (33%) of hepatocellular carcinoma (HCC) cases." (PMID 22401581, 2012).